CXCR4 (C-X-C motif chemokine receptor 4)
Diseases named in the same sentence as CXCR4 in open-access papers (continued):
Sharing a sentence is not in itself a finding about the gene and the disease.
myelofibrosis (6 papers, 2014 to 2022). A partial or complete replacement of the bone marrow stroma by fibrous tissue. "The CXCL12/CXCR4 pathway can be induced by oncogenic JAK2, which frequently suffers activating mutations in primary myelofibrosis, and JAK2 inhibition can reduce the chemotaxis of hematopoietic cells isolated from primary myelofibrosis." (PMID 35356507, 2022). "CXCL12/CXCR4 pathway is activated by oncogenic JAK2, which frequently suffers activating mutations in primary myelofibrosis." (PMID 35356507, 2022). "We and others have previously reported CXCR4 to be significantly downregulated in MPNs, in particular in myelofibrosis, consistent with previous studies displaying downregulation of CXCR4 in CD34+ cells." (PMID 35771847, 2022). "Highly interesting, CXCR4 was significantly downregulated across all three MPN categories being most pronounced in patients with myelofibrosis." (PMID 25397683, 2014). "Thus, reduced CXCR4 expression has been reported on circulating CD34+ cells from patients with myelofibrosis." (PMID 24454890, 2014). "Therefore, CXCL12 may also be involved in protecting the leukemic stem cells and contributing to myelofibrosis progression, though CXCR4 is downregulated in the malignant progenitors, which may explain extramedullary clonal hematopoiesis in myelofibrosis." (PMID 35356507, 2022). "Additionally, other CXCR4/CXCL12 inhibitors have shown synergy with ICIs in vitro and these combination regimens are now being assessed in clinical trials for PDAC and myelofibrosis (NCT04177810, NCT02826486, NCT03168139, and NCT04177810)." (PMID 35797269, 2022). "Importantly, upregulation of CXCL12, ASPN, and OLFM3, factors secreted by CAF, has been observed; CXCL12, through the interaction with its receptor CXCR4, can lead to CXCL12 and TGFβ production and concur to myelofibrosis." (PMID 29515580, 2018).
neuroendocrine carcinoma (6 papers, 2019 to 2025). A malignant neuroendocrine neoplasm composed of cells containing secretory granules that stain positive for NSE and chromogranin. "Ga-68 CXCR4 (Ga-68 PentixaFor) binds to a C-X-C chemokine receptor (CXCR4), which is often overexpressed in poorly differentiated NETs, also referred to as neuroendocrine carcinomas (NECs)." (PMID 40563663, 2025). "MS-18 represents the CXCR4-expressing neuroendocrine carcinoma phenotype better than the other cell lines studied." (PMID 33671498, 2021). "Since CXCR4 presence was inversely correlated with SST2A expression especially in high-grade neuroendocrine carcinomas of the appendix or colon, this receptor may represent an interesting new target structure, which should be validated in further studies." (PMID 30867449, 2019). "A, B A 75-year-old patient with pretreated gastric neuroendocrine carcinoma (NEC) and a negative CXCR4 PET scan with missing tracer uptake of the liver metastases." (PMID 38332341, 2024).
retinoblastoma (6 papers, 2014 to 2025). A malignant tumor that originates in the nuclear layer of the retina. "This triple approach of pH-activated cytotoxic nanoceria, the CXCR4 antagonist and the traditional chemotherapeutic agent, doxorubicin, demonstrated a synergistic effectiveness against retinoblastoma, both in vitro and in vivo." (PMID 40227824, 2025). "The chemokine receptor CXCR4 has been found to be overexpressed in various cancers, and the group showed that retinoblastoma is amongst those." (PMID 40227824, 2025). "Expression of CXCR4 was previously observed in tumor cells isolated from retinoblastoma, the most common intraocular malignancy in children." (PMID 35335871, 2022). "USMB enhanced the paracellular permeability of an anti-CXCR4 nanobody and its subsequent binding to retinoblastoma cells." (PMID 35335871, 2022). "In clinical practice, USMB could be used to enhance the distribution of the anti-CXCR4 nanobody in the retina, and improve the efficacy of anti-cancer treatment in retinoblastoma." (PMID 35335871, 2022). "For example, USMB might make it possible to deliver anti-CXCR4 nanobody to retinoblastoma cells, allowing for increased nanobody binding to tumor cells and inhibiting their migration and proliferation." (PMID 35335871, 2022). "CXCR4 is overexpressed in a number of cancer cells including retinoblastoma cells in the eye." (PMID 35335871, 2022). "Finally, combination of USMB with pharmaceuticals (such as an anti-CXCR4 nanobody for the treatment of retinoblastoma) could be tested in in vivo disease models in order to determine the therapeutic efficacy of the method." (PMID 35335871, 2022). "Moreover, NEAT1 could regulate the proliferation, migration, and apoptosis of human retinoblastoma cells via regulation of the miR-204/CXCR4 axis." (PMID 32596382, 2020). "In the case of the clinically relevant anti- C-X-C Chemokine Receptor Type 4 (CXCR4) nanobody (molecular weight 15 kDa), USMB enhanced paracellular permeability by two-fold and increased binding to retinoblastoma cells by five-fold." (PMID 35335871, 2022).
soft tissue sarcoma (6 papers, 2011 to 2024). A malignant neoplasm arising from muscle tissue, adipose tissue, blood vessels, fibrous tissue, or other supportive tissues excluding the bones. "Moreover, CXCR4 expression has been associated with poor survival in bone and soft-tissue sarcomas and many types of carcinomas." (PMID 28386296, 2017). "The prognostic significance of CXCR4 has been studied in detail in patients with bone and soft tissue sarcomas." (PMID 31428099, 2019). "CXCR4 expression has been related with poor prognosis in patients with bone and soft-tissue sarcomas in a meta-analysis." (PMID 28386296, 2017). "CXCR4 appears to be a useful prognostic marker for multiple histologic subtypes of soft tissue sarcoma." (PMID 21234386, 2011). "We have recently demonstrated that YY1 is involved in CXCR4 and VEGF pathways which have both been genetically amplified and correlated with poor survival of soft-tissue sarcomas." (PMID 22047406, 2011). "There was also a significant correlation between CXCR4 and expression of VEGF in this group of soft tissue sarcomas." (PMID 21234386, 2011).
abdominal aortic aneurysm (5 papers, 2021 to 2025). Enlargement and ballooning of the vessel that supplies arterial blood to the abdomen, pelvis and legs. "Recent findings have revealed that CXCR4 is associated with angiogenesis, inflammatory cell migration, and proliferation in IA walls and that it may play an important role in inflammatory activity in the abdominal aortic aneurysm (AAA) wall." (PMID 33867914, 2021). "In the field of cardiovascular disease, CXCR4 has been demonstrated to be overexpressed in abdominal aortic aneurysm (AAA) tissues." (PMID 40342960, 2025). "Previous studies have shown that T and B cells infiltrated in abdominal aortic aneurysms are CXCR4-positive and are recruited by CXCL12-positive stromal cells." (PMID 35837612, 2022). "Notably, the C‐X‐C Motif Chemokine Ligand 12/C‐X‐C Chemokine Receptor Type 4 (CXCL12/CXCR4) signalling pathway's activation is markedly increased in a mouse model of abdominal aortic aneurysms (AAA)." (PMID 39779470, 2025).
acute lung injury (5 papers, 2019 to 2025). A condition of lung damage that is characterized by bilateral pulmonary infiltrates (pulmonary edema) rich in neutrophils, and in the absence of clinical heart failure. "Another study was focused on the C-X-C chemokine receptor type 4 gene CXCR4 implicated in acute lung injury (ALI), a life-threatening condition associated with increased permeability of the alveolar-capillary barrier." (PMID 32599709, 2020). "AMD3100, a CXCR4 antagonist, has beneficial effects immaculate in the treatment of acute lung injury (ALI)." (PMID 39677961, 2024). "Recent evidence has shown that C-X-C chemokine receptor type 4 (CXCR4) plays a crucial role in acute lung injury (ALI)." (PMID 31304005, 2019).
adenomyosis (5 papers, 2020 to 2026). The growth of endometrial tissue inside the muscular wall of the uterine corpus. "The levels of CXCL12 and its receptor, chemokine (C-X-C motif) receptor 4 (CXCR4), were found to be significantly increased in both eutopic and ectopic endometrium from patients with adenomyosis." (PMID 35022045, 2022). "Semi‐quantitative detection showed that mifepristone‐treated adenomyosis group significantly decreased the expression of CXCR4 in both eutopic and ectopic endometriums when compared to mifepristone‐untreated group." (PMID 31814282, 2020). "The result of RNA sequencing showed that mRNA expression of CXCR4 was down‐regulated in the endometrial epithelial cells of adenomyosis by mifepristone treatment." (PMID 31814282, 2020). "Immunohistochemistry staining also showed that CXCR4 expression was significantly decreased in mifepristone‐treated adenomyosis group." (PMID 31814282, 2020). "To confirm the role of CXCR4 in the migration of adenomyosis, we detected the migration ability of eutopic endometrial epithelial cells and stromal cells treated with different doses of CXCR4 inhibitor (AMD3100) using transwell assay." (PMID 31814282, 2020). "qRT‐PCR analysis and Western blotting further validated that mifepristone could inhibit CXCR4 expression in primary endometrial epithelial cells and stromal cells of adenomyosis in a dose‐dependent manner." (PMID 31814282, 2020). "In addition, transwell assay was then performed to confirm that CXCR4 increased the migration of eutopic endometrial epithelial cells and stromal cells in adenomyosis." (PMID 31814282, 2020). "We found that AMD3100 greatly suppressed the migratory activity of eutopic endometrial epithelial cells and stromal cells in a dose‐dependent manner, which suggested that CXCR4 promotes the migratory capacity of eutopic endometrial epithelial cells and stromal cells in adenomyosis." (PMID 31814282, 2020). "Therefore, we conclude that mifepristone inhibits the migration capacity of the eutopic endometrial epithelial cells and stromal cells through suppressing CXCR4 expression in adenomyosis." (PMID 31814282, 2020). "CXCR4, one of the most prevalent chemokine receptors, can promote the migration of many different types of cancer cells while it was significantly down‐regulated in the primary endometrial epithelial cells of adenomyosis after treated with mifepristone by analysis of RNA‐Seq data." (PMID 31814282, 2020). "Furthermore, mifepristone inhibits the migration of endometrial epithelial cells and stromal cells through decreasing CXCR4 expression and restricts the invasion of endometrial epithelial cells via suppression of epithelial‐mesenchymal transition in adenomyosis." (PMID 31814282, 2020). "Furthermore, mifepristone inhibits the migration of endometrial epithelial cells and stromal cells through decreasing CXCR4 expression and restricts the invasion of endometrial epithelial cells via suppression of EMT process in adenomyosis." (PMID 31814282, 2020). "Subsequently, immunohistochemistry was conducted to detect the protein expression of CXCR4 in eutopic and ectopic endometriums of adenomyosis patients with and without mifepristone treatment." (PMID 31814282, 2020).
aplastic anemia (5 papers, 2017 to 2022). Anemia resulting from bone marrow failure (aplastic or hypoplastic bone marrow). "CXCR4 expression facilitates pathogenic T-cell trafficking in the BM of murine Aplastic Anemia model." (PMID 30038265, 2018). "The SDF-1/CXCR4 axis has been shown to improve the recruitment and hematopoietic reconstitution of bone marrow-derived MSCs in aplastic anemia." (PMID 33467640, 2021). "Additional trials are ongoing for the CXCR4 antagonist BL-040 in NSCLC (NCT03337698), in AML in combination with atezolizumab (NCT03154827), in metastatic pancreatic cancer (NCT02907099), and in aplastic anemias or hypoplastic myelodysplastic Syndrome (NCT02462252) and several others." (PMID 30873179, 2019).
atopic dermatitis (5 papers, 2021 to 2025). "CXCR4 expression is increased in atopic dermatitis skin lesions, and CXCR4/CXCL12 signaling in keratinocytes contributes to the infiltration of inflammatory cells, such as T cells and eosinophils, into the skin." (PMID 38256077, 2024). "As a novel and potent CXCR4 antagonist, EPI-X4 JM#21 is positioned in the text as a first-in-class inhibitor with therapeutic efficacy in treating atopic dermatitis, highlighting its importance." (PMID 39070795, 2024).
brain cancer (5 papers, 2016 to 2023). A primary or metastatic malignant neoplasm affecting the brain. "Previous studies showed PDGF-D facilitated tumor invasion and metastasis by activating Notch1, PI3K, ERK, or CXCR4 pathways in breast, lung and brain cancers." (PMID 28035069, 2017).
cardiomyopathy (5 papers, 2015 to 2023). A disease of the heart muscle or myocardium proper. "Supporting our data, a recently published study showed that cardiomyocyte specific deletion of the CXCL12 corresponding receptor CXCR4 in mice leads to progressive cardiomyopathy with significant tissue fibrosis." (PMID 34072818, 2021). "Following these animals over the 12-month study period has allowed us to demonstrate the development of a progressive cardiomyopathy as the animals aged; CXCR4 cKO hearts demonstrated abnormalities in both structure and contractile function." (PMID 31071921, 2019). "We showed that in a mouse model of DOXO-induced cardiomyopathy, CXCR4+ cells were increased in response to DOXO, mainly in human cardiac mesenchymal progenitor cells (CmPC), a subpopulation with regenerative potential." (PMID 28837147, 2017). "However, in non-ischaemic cardiomyopathies like DCM the interaction of SDF-1 with CXCR4 does not seem to be the important driver of migration, because SDF-1 expression was not up-regulated in cardiac tissue of humans and mice with DCM 16,24." (PMID 25754690, 2015).
cerebral infarction (5 papers, 2019 to 2025). An ischemic condition of the brain, producing a persistent focal neurological deficit in the area of distribution of the cerebral arteries. "The present study takes advantage of the important role of the CXCL12/CXCR4 axis in the recovery of cerebral infarction." (PMID 33381162, 2020). "The CXCR4 antagonist AMD3100 blocks the interaction between CXCR4 and CXCL12, which not only alleviates cerebral inflammation and cerebral infarction but also prevents splenic atrophy after tMCAO." (PMID 30700305, 2019).
cystitis (5 papers, 2008 to 2023). Inflammation of the urinary bladder. "Our lab examined the expression and therapeutic effect with receptor blockade of the chemokine CXCL12, and one of its two receptors, CXCR4, in a rodent model of cystitis." (PMID 24738044, 2014). "We studied whether CXCR4-MIF associations occur in rat bladder and the effect of experimental cystitis." (PMID 19066630, 2008). "Our results show that both CXCR4 and SDF-1 are constitutively expressed in normal rat bladder and upregulated during CYP-induced cystitis." (PMID 19066630, 2008). "Macrophage migration inhibitory factor (MIF) is a pro-inflammatory cytokine involved in cystitis and a non-cognate ligand of the chemokine receptor CXCR4 in vitro." (PMID 19066630, 2008).
endotoxemia (5 papers, 2015 to 2025). "In contrast, others have used a model of endotoxemia to show that aged CXCR4+ circulating PMNs rapidly migrate to the site of inflammation rather than returning to bone marrow." (PMID 36712325, 2022). "The present results are consistent with previous findings, in which different CXCR4 agonists were found to exert beneficial effects in endotoxemia in vivo." (PMID 27716214, 2016). "This suggests that interruption of the CXCR4/CXCL12 axis is deleterious in acute inflammation and confirms previous findings showing beneficial effects of CXCR4 agonists in endotoxemia, thereby more clearly elucidating the role of CXCR4 in inflammation." (PMID 27716214, 2016). "In summary, in the present investigation, we demonstrated that CXCR4 blockade with AMD3100 exerts deleterious effects in multiple facets of endotoxemia." (PMID 27716214, 2016). "We hypothesized that several effects might only become visible by antagonizing the receptor, rather than administering a CXCR4 agonist, enabling us to understand the impact of CXCR4 in endotoxemia." (PMID 27716214, 2016). "Consequently, we intended to understand the impact of CXCR4 in endotoxemia more precisely and to explore its influence in inflammation from another perspective." (PMID 27716214, 2016). "In contrast to other studies, which focused mainly on the general outcome of the animals and on the migration of several inflammatory cell populations in different inflammation models, we were primarily interested in the precise effects of CXCR4 blockade in endotoxemia." (PMID 27716214, 2016). "We focused mainly on the health status of treated mice and specifically, whether a CXCR4 blockade would worsen endotoxemia, as suggested previously." (PMID 27716214, 2016). "Furthermore, we investigated whether CXCR4 blockade exerts deleterious effects, thereby substantiating previous studies showing a beneficial outcome after treatment with CXCR4 agonists in endotoxemia." (PMID 27716214, 2016). "However, little is known regarding the precise effects of CXCR4 blockade in endotoxemia." (PMID 27716214, 2016). "In accordance with previous investigations, which found that CXCR4 agonists reduce serum levels of pro-inflammatory cytokines in endotoxemia, we detected increased levels of serum TNF alpha and IFN gamma after CXCR4 blockade." (PMID 27716214, 2016). "Also, we aimed to indirectly show that CTCE-0214D signals through CXCR4 and to further unravel whether an interruption of the CXCR4/CXCL12 axis results in a deleterious outcome in endotoxemia." (PMID 27716214, 2016). "In addition, by detecting effects with the CXCR4 antagonist, AMD3100, that are in direct contrast to those observed with the CXCL12 analog, CTCE-0214D, in endotoxemia, we can hypothesize that treatment with CTCE-0214D exerts its protective effects mainly via CXCR4." (PMID 27716214, 2016).
glomerulonephritis (5 papers, 2019 to 2024). A renal disorder characterized by damage in the glomeruli. "SLE-associated glomerulonephritis is accompanied by hyperplastic kidney lesions caused by CXCR4 dysregulation in kidney epithelial cells." (PMID 39070795, 2024). "in which they demonstrated the significance of TLR4+CXCR4+ PCs for autoantibody production and glomerulonephritis development in LN." (PMID 37872565, 2023). "In glomerulonephritis, CXCR4 is overexpressed in parietal epithelial cells of the kidney, triggering their migration into the glomerular tuft where they form hyperplastic lesions." (PMID 32252660, 2020). "Small molecule MIF antagonists also resulted in reduced glomerulonephritis and interstitial inflammation, lower levels of CD74+ and CXCR4+ leukocyte recruitment and decreased circulating TNF-α." (PMID 30787934, 2019).
Hodgkins lymphoma (5 papers, 2013 to 2023). A heterogeneous group of malignant lymphoid neoplasms of B-cell origin characterized histologically by the presence of Hodgkin and Reed-Sternberg (HRS) cells in the vast majority of cases. "There is strong evidence showing that luteolin has great effects on inhibiting the growth of cancer cells in Classical Hodgkin’s Lymphoma via caspase activated-cell death, which is characterized by the reduction of C-X-C chemokine receptor type 4 (CXCR4), matrix metalloproteinase (MMP)-2 and MMP-9." (PMID 36673411, 2023). "FISH and PCR analyses showed that these two Hodgkin lymphoma-derived hybrid tumors displayed both hamster and human DNA in the same nuclei by FISH, while also retaining the human genes, CD74, CXCR4, CD19, CD20, CD71, CD79b, and VIM." (PMID 25259521, 2014).